VDR (vitamin D receptor)
Diseases named in the same sentence as VDR in open-access papers (continued):
Sharing a sentence is not in itself a finding about the gene and the disease.
breast tumors (continued). "TN aggressive human breast tumors as well as transplantable xenografts obtained from SKBR3 expressed significantly lower levels of VDR but higher levels of CD44 expression." (PMID 23341935, 2013). "In comparison to the normal breast tissues, the 1α-hydroxylase/28S rRNA ratio was somewhat lower (1 ± 0.07 versus 0.7 ± 0.05, p < 0.001) and the VDR/28S rRNA ratio somewhat higher (1 ± 0.09 versus 1.4 ± 0.12, p < 0.05) in the breast tumor specimens." (PMID 16280049, 2005). "The primary aim of the present study was to analyze if pre-diagnostic systemic levels of vitamin D were associated with VDR expression in subsequent breast tumors, as we have found no previous study investigating this relationship." (PMID 36014861, 2022). "Many small studies have evaluated whether VDR protein expression (assessed by immunohistochemistry) in human breast tumors correlates with disease status." (PMID 34950835, 2021). "Contrary to what might be expected based on in vitro studies, human breast tumors with both high and low VDR expression were present in this population, making it difficult to interpret the impact of VDR expression on survival using the entire data set." (PMID 34950835, 2021). "Due to this hypothesis, high levels of VDR might be typical for breast tumors with high level of nuclear CTLS and TP53BP1." (PMID 32456160, 2020). "All three steroid receptors analyzed by immunohistochemistry, namely, the estrogen receptor (ER), the progesterone receptor (PR), and the vitamin D receptor (VDR), showed a significantly positive influence on the course of the disease, but only for the unifocal breast tumor patients." (PMID 31731733, 2019). "VDR expression was evaluated in a tissue microarray of 718 invasive breast tumors." (PMID 31358030, 2019). "Alterations in the VDR gene were present in only 5% of human breast tumors." (PMID 26000308, 2015). "Interestingly, this study also demonstrated that breast tumors with the highest expression of VDR, ER, and Androgen Receptor (AR) had the best prognosis." (PMID 24982636, 2014). "Only 5% of human breast tumors exhibited any alteration in VDR sequence or expression." (PMID 24982636, 2014). "The significance of this study is that it demonstrated for the first time that 1,25(OH)2D3 could induce genomic changes in intact breast tumor tissue, indicating the functionality of the VDR." (PMID 24982636, 2014). "Earlier reports have shown that high VDR and Eag1 expression is characteristic of breast tumors." (PMID 22984610, 2012). "Moreover, VDR expression were remarkably lower in ER- than in ER+ breast tumors, and the elevation of VDR nuclear corepressor NCoR1 level was particularly associated with ER negativity." (PMID 21386992, 2011). "In summary, although low VDR expression in breast tumors may correlate with reduced survival, high VDR expression does not associate with better survival." (PMID 34950835, 2021). "Previous studies have suggested that the vitamin D receptor may be overexpressed in breast tumors." (PMID 16542425, 2006). "Frequency of genomic alterations in VDR and CYP24A1 derived from The Cancer Genome Atlas dataset of human breast tumors." (PMID 24982636, 2014). "Further, our studies showed that VDR expression was suppressed while CD44 was up-regulated in transplantable xenografts (TX), ALDH+ population enriched in MCSCs as well as in aggressive breast tumors." (PMID 23341935, 2013). "Further experiments have shown upregulation of VDR, MALAT1 and LINC00511 in breast tumors relative to nearby non-cancerous samples, and associations between clinicopathological data and expression of VDR-associated lncRNAs." (PMID 38475720, 2024). "Women with high levels of vitamin D had a smaller proportion of VDR negative breast tumors compared to women with low levels of vitamin D (odds ratio: 0.68; 95% confidence interval: 0.41–1.13)." (PMID 36014861, 2022). "All cultured breast tumor-derived cells were positive for VDR and further confirmed to be negative for ERα." (PMID 24678876, 2014).
breast tumors (continued). "Unlike MCSCs and aggressive breast tumors, high levels of functional VDR have been found in normal mammary glands mediating the effects of 1,25D on growth and differentiation of these cells." (PMID 23341935, 2013). "In this study we show that the anti-proliferative effects of 1,25D may be functional in MCF7 breast tumor cell lines, without a role for the central player in calcium homeostasis, VDR." (PMID 19863778, 2009). "The antiproliferative activity of compound 29 was determined to be dependent on the Vitamin D Receptor (VDR), as it failed to inhibit the proliferation of breast tumor cells derived from animals lacking VDR." (PMID 40299638, 2025).
preeclampsia (34 papers, 2014 to 2025). Preeclampsia is a hypertensive disorder of pregnancy that is characterized by new-onset hypertension with proteinuria presenting after 20 weeks of gestation, and depending on mild or severe forms may initially present with severe headache, visual disturbances, and hyperreflexia. "Genetic polymorphisms in the VDR gene have been associated with altered vitamin D metabolism and increased preeclampsia risk." (PMID 41301719, 2025). "The VDR rs7975232 polymorphism was associated with higher BMI and systolic blood pressure and lower vitamin D levels and was also associated with preeclampsia." (PMID 39408215, 2024). "This study therefore investigated the interplay between vitamin D status and VDR gene variants in association with preeclampsia risk in the Ghanaian population." (PMID 38814968, 2024). "Variability within the VDR gene, is known to influence its protein levels and their stability, potentially contributing to the risk of developing preeclampsia." (PMID 38814968, 2024). "We assessed the interplay between Vitamin D, VDR gene variants and preeclampsia risk in Ghanaian women." (PMID 38814968, 2024). "The findings suggest a complex association between vitamin D, VDR gene variants, and preeclampsia among Ghanaian women." (PMID 38814968, 2024). "This study investigated the relationship between vitamin D levels, VDR gene variants, and the risk of developing preeclampsia in Ghanaian women." (PMID 38814968, 2024). "We identified that PEGIL11 treatment significantly regulated the placental production of multiple factors previously associated with preeclampsia including alpha-fetoprotein, angiotensinogen, apolipoproteins A1 and B, and vitamin D receptor." (PMID 37292200, 2023). "Our results showed that placental LAT1 expression was reduced in women with preeclampsia compared to normotensive pregnancies, which was associated with decreased expression of vitamin D receptor (VDR)." (PMID 35301401, 2022). "For the first time in the Polish population, we aimed to investigate associations between the VDR gene single-nucleotide polymorphisms (SNPs) BsmI (rs15444410), ApaI (rs7975232), FokI (rs19735810), and TaqI (rs731236) and the development of preeclampsia (PE)." (PMID 34574039, 2021). "Vitamin D receptor polymorphisms related to FokI, ApaI, and TaqI were reported to be associated with gestational diabetes mellitus, pre-preeclampsia, and preterm birth." (PMID 32397276, 2020). "Otherwise, the VDR FokI variant was associated with decreased risk of preeclampsia in the dominant model in Iranian population." (PMID 31892349, 2019). "The meta‐analytic approach also revealed relationships between SNPs in the flanking and noncoding regions of GC and VDR with preeclampsia risk." (PMID 29380949, 2018). "In the multivariate and univariate analyses, two SNPs in the flanking and noncoding regions SNPs in VDR and three SNPs in the flanking and noncoding regions in GC were associated with preeclampsia risk." (PMID 29380949, 2018). "Several SNPs in the noncoding and flanking regions of VDR were associated with preeclampsia risk in the univariate and multivariable analysis." (PMID 29380949, 2018). "Dysregulation of vitamin D metabolism—such as downregulation of CYP2R1 and VDR—has been linked to gestational diabetes and preeclampsia and may impair calcium signaling and increase oxidative stress, thereby reducing neonatal bone mineral content." (PMID 40590014, 2025). "A large Chinese cohort also reported null associations, but identified vitamin D receptor gene polymorphisms that may influence susceptibility to preeclampsia." (PMID 41301719, 2025). "A much larger sample size might be required in future studies to augment associations, particularly VDR gene variant and preeclampsia in the Ghanaian population." (PMID 38814968, 2024). "The VDR rs1544410 bb genotype reduced the risk of preeclampsia." (PMID 39408215, 2024).
preeclampsia (continued). "In examining the role of specific VDR gene variants and PE risk, it was observed that individuals with the "bb" genotype (homozygous for the recessive Bsm1 allele) had a reduced risk of developing preeclampsia." (PMID 38814968, 2024). "It is likely the ‘bb’ genotype may modulate transcription and translation of the VDR protein leading to adequate vitamin D levels and ultimately reduce preeclampsia risk." (PMID 38814968, 2024). "Besides, activation of VDR prevented pathological dedifferentiation of pancreatic beta cells, and downregulation of VDR increased endothelial inflammatory response in preeclampsia, further shed light on the potential associations between vitamin D and MetS." (PMID 35093150, 2022). "However, a case-control study showed that the VDR FF/bB haplotype resulted in a double increase to the risk for gestational hypertension in vitamin D-deficient pregnant women." (PMID 35627905, 2022). "Considering the important role of vitamin D and its receptor in the development of physiological pregnancy and the possible influence of vitamin D deficiency on the occurrence of preeclampsia, it can be assumed that VDR gene polymorphisms influence the development of preeclampsia." (PMID 34574039, 2021). "Minor allele of a noncoding region of the VDR gene was significantly associated with preeclampsia risk, which was verified in the meta‐analysis [odds ratio (OR), 95% confidence intervals (CI)] after adjusting for multiple comparisons [rs12831006:1.5 (1.2, 2.0), P < 0.0001]." (PMID 29380949, 2018). "Furthermore, this study focused on a specific subset of VDR gene variants, and other polymorphisms that might contribute to preeclampsia susceptibility warrant exploration." (PMID 38814968, 2024). "Further research is needed to identify the functionality of VDR and GC SNPs, to test interactions and associations between 25(OH)D and these allelic variants, to test SNP‐SNP epistatic effects, and to identify if SNPs in other vitamin D related genes have a relationship with preeclampsia risk." (PMID 29380949, 2018). "Therefore, hypermethylation of VDR gene may cause the downregulation of placental VDR in FGR-or preeclampsia." (PMID 29113124, 2017). "Previous research has linked VDR gene variations to infertility in women and men due to PCOS, endometriosis, preeclampsia, idiopathic infertility, and other causes." (PMID 38816754, 2024). "However, "bb" genotype of the VDR Bsm1 variant may decrease the risk for preeclampsia." (PMID 38814968, 2024). "Previous research by our team demonstrated that VD improved the inflammatory response of the placenta, reduced the risk of preeclampsia (PE), and regulated the miR26b-5p-COX2 pathway through the VDR." (PMID 37894993, 2023). "Conclusively, downregulation of VDR and miR-26b-5p expression was associated with upregulation of COX-2 expression in the placentas from women with preeclampsia." (PMID 34045549, 2021). "In the present study, we found that placental VDR expression was reduced in women with preeclampsia." (PMID 34045549, 2021). "We first determined if aberrant VDR expression and miR-26b-5p expression are present in the placentas of women with preeclampsia." (PMID 34045549, 2021). "Our findings of decreased VDR and miR-26b-5p expression related to increased COX-2 expression in the placenta suggest that reduced VDR expression and miR-26b-5p expression are connected to increased placental inflammatory response in preeclampsia." (PMID 34045549, 2021). "Our results clearly showed that VDR expression was markedly reduced in the placenta and primary isolated placental trophoblasts from women with preeclampsia." (PMID 34045549, 2021). "Collecting with the current finding, we believe that downregulated placental VDR and miR-26b-5p expression contributes to the increased inflammatory response in preeclampsia." (PMID 34045549, 2021).
preeclampsia (continued). "The most relevant targets for preeclampsia were: AR, VDR, SLC6A2, NOS3 and CHRM4, while ABCG2, ERBB2, CES1 and REN led to the most relevant off-targets." (PMID 33546161, 2021). "In the present study, we had important findings that placental expression of VDR and miR-26b-5p was markedly reduced in women with preeclampsia compared to normotensive pregnant women." (PMID 34045549, 2021). "Vitamin D and intracellular VDR are strongly related to the trophoblast survival capacity in preeclampsia." (PMID 30408071, 2018). "Late-onset and early-onset preeclampsia groups had lower mean values of VDR staining compared to the normal pregnancy group." (PMID 30408071, 2018). "This review highlights the role of the vitamin D receptor in physiologic and disturbed pregnancy, as preeclampsia, fetal growth restriction, gestational diabetes and preterm birth." (PMID 29113124, 2017). "In a subgroup, mRNA expression of CYP24A1 (24-hydroxylase), CYP27B1 (1α-hydroxylase) and VDR (vitamin D receptor) were quantified by real time PCR in placental samples of 14 women with normal pregnancies and 13 with preeclampsia." (PMID 25148115, 2014). "The results suggest that VDR activation by VD supplementation upregulates the expression of its downstream target gene VEGF and reduces the risk of adverse outcomes, such as gestational hypertension, preeclampsia, and offspring preterm delivery caused by maternal VD deficiency during pregnancy." (PMID 36296914, 2022). "According to our best knowledge, there have been no studies evaluating the frequency of VDR gene polymorphisms in the Polish population of pregnant women with preeclampsia that have been published." (PMID 34574039, 2021). "The upregulation of miR-26b-5p expression stimulated by vitamin D/VDR signaling may be a novel mechanism of the anti-inflammatory activity of vitamin D in preeclampsia." (PMID 34045549, 2021). "If our results linking SNPs in VDR and GC with preeclampsia are confirmed, then allelic variation may have an important role in the relationship between vitamin D and preeclampsia." (PMID 29380949, 2018). "Vitamin D and its cellular binding component vitamin D receptor (VDR) might play a role in the trophoblast survival capacity particularly in preeclampsia." (PMID 30408071, 2018). "Finally, there was a strong and significant negative correlation between the survival capacity (MAP1LC3B/BECN1) and both maternal vitamin D and placental VDR in the preeclampsia groups." (PMID 30408071, 2018). "Furthermore, there was a strong and significant correlation between the MAP1LC3B/BECN1 ratio as survival marker and VDR levels in the early-onset preeclampsia group." (PMID 30408071, 2018). "VDR polymorphisms do not appear to predispose women to preeclampsia and gestational hypertension and VDR expression is similar between normal placentae and those from pregnancies complicated by gestational diabetes." (PMID 26121239, 2015). "Neither VDR Taq1 nor VDR BmsI was associated with the risk of preeclampsia." (PMID 39408215, 2024). "In addition, down-regulation of VDR promotes endothelial inflammatory responses in preeclampsia." (PMID 36672270, 2023). "While the relationship between VDR and foetal outcomes such as newborn anthropometry remains unclear, the role of VDR in normal and abnormal pregnancy conditions such as preeclampsia, foetal growth restriction, gestational diabetes and preterm birth have been reported in previous studies." (PMID 36071390, 2022). "We previously found that VDR and miR-126 expression was reduced in maternal systemic endothelial cells in preeclampsia, and that, vitamin D could inhibit TNF-α-induced vascular cell adhesion molecule (VCAM) expression/production in endothelial cells by promoting miR-126 expression." (PMID 34045549, 2021).